B3GALNT2 (beta-1,3-N-acetylgalactosaminyltransferase 2)
Description:
Beta-1,3-N-acetylgalactosaminyltransferase that synthesizes a unique carbohydrate structure, GalNAc-beta-1-3GlcNAc, on N- and O-glycans. Has no galactose nor galactosaminyl transferase activity toward any acceptor substrate. Involved in alpha-dystroglycan (DAG1) glycosylation: acts coordinately with GTDC2/POMGnT2 to synthesize a GalNAc-beta3-GlcNAc-beta-terminus at the 4-position of protein O-mannose in the biosynthesis of the phosphorylated O-mannosyl trisaccharide (N-acetylgalactosamine-beta-3-N-acetylglucosamine-beta-4- (phosphate-6-)mannose), a carbohydrate structure present in alpha-dystroglycan, which is required for binding laminin G-like domain-containing extracellular proteins with high affinity.
Synonyms: MGC39558; B3GalNAc-T2; MDDGA11
Tractability: Antibody: UniProt predicts a signal peptide or a membrane-spanning region. PROTAC: ubiquitination databases record sites on it.
Gene: Protein-coding gene on chromosome 1 (235,447,190 to 235,504,474, reverse strand). Ensembl gene ENSG00000162885.
Subcellular location: Golgi apparatus membrane; Endoplasmic reticulum
Subcellular location (Human Protein Atlas): Golgi apparatus
Pathways (Reactome):
Metabolism of proteins: DAG1 core M3 glycosylations
Gene Ontology:
Molecular function: acetylgalactosaminyltransferase activity; protein binding; UDP-glycosyltransferase activity; hexosyltransferase activity
Biological process: glycoprotein biosynthetic process; protein O-linked glycosylation
Cellular component: endoplasmic reticulum; endoplasmic reticulum membrane; Golgi membrane; membrane
Genetic constraint (gnomAD): Loss-of-function variants: 54 observed, 65.1 expected, observed/expected ratio (o/e) 0.83, 90% interval 0.67 to 1.04. The upper end of that interval is the gene's LOEUF score, 1.04, which puts it in group 4 of 6, group 1 being the genes least tolerant of losing a copy. Missense variants: 526 observed, 612.1 expected, observed/expected ratio (o/e) 0.86, 90% interval 0.8 to 0.92. Synonymous variants: 219 observed, 227.43 expected, observed/expected ratio (o/e) 0.96, 90% interval 0.86 to 1.08.
Gene-disease validity (ClinGen):
ClinGen rates the evidence that B3GALNT2 causes each of these diseases.
muscular dystrophy-dystroglycanopathy (congenital with brain and eye anomalies), type a, 11 (autosomal recessive): Definitive. Any muscular dystrophy-dystroglycanopathy, type A in which the cause of the disease is a mutation in the B3GALNT2 gene.
Homologues: Orthologues: chimpanzee B3GALNT2 (99% identical), macaque B3GALNT2 (98% identical), pig B3GALNT2 (92% identical), dog B3GALNT2 (92% identical), guinea pig B3GALNT2 (91% identical), mouse B3galnt2 (88% identical), rat B3galnt2 (88% identical), rabbit B3GALNT2 (85% identical), tropical clawed frog b3galnt2 (69% identical), zebrafish b3galnt2 (52% identical), Drosophila melanogaster brn (13% identical), Caenorhabditis elegans bre-5 (12% identical), and 2 more. Paralogues in human: B3GALT2 (17% identical), B3GNT4 (15% identical), B3GNT8 (15% identical), B3GALNT1 (14% identical), B3GALT4 (14% identical), B3GNT6 (14% identical), B3GNT9 (14% identical), B3GNT3 (14% identical), B3GALT6 (14% identical), B3GNT5 (14% identical), B3GNT7 (14% identical), B3GNT2 (13% identical), and 3 more.
Diseases named in the same sentence as B3GALNT2 in open-access papers:
B3GALNT2 is named in the same sentence as 29 diseases in open-access papers, as found by Europe PMC text mining. Sharing a sentence is not in itself a finding about the gene and the disease. The quoted sentences say what the papers report.
muscular dystrophy (6 papers, 2014 to 2022). Muscular dystrophy (MD) refers to a group of more than 30 genetic diseases characterized by progressive weakness and degeneration of the skeletal muscles that control movement. "Earlier we found a nonsense mutation in B3GALNT2 involved in muscular dystrophy with hydrocephalus in stillborn foals." (PMID 27793082, 2016). "The nonsense mutation XM_001491545 c.1423C>T corresponding to XP_001491595 p.Gln475* was identical to a B3GALNT2 mutation identified in a human case of muscular dystrophy-dystroglycanopathy with hydrocephalus." (PMID 26452345, 2015). "Nine different mutations were observed in the B3GALNT2 gene in 6 human patients with muscular dystrophy-dystroglycanopathy with brain and eye anomalies, type A, 11 (MDDGA11 [MIM:615181])." (PMID 26452345, 2015). "In addition, we could identify abnormal serum glycoproteins in LARGE and B3GALNT2-deficient muscular dystrophies." (PMID 27134828, 2016). "Within congenital muscular dystrophies, the gene B3GALNT2, ranked in the 97th place out of 4841 genes with annotation for this group's signature, was recently found to be associated with hypoglycosylation of alpha-dystroglycan and a congenital muscular dystrophy phenotype in humans." (PMID 25353622, 2014). "In humans, a muscular dystrophy-dystroglycanopathy phenotype [MDDGA11, MIM:615181] including hydrocephalus has recently been associated with mutations in B3GALNT2." (PMID 26452345, 2015). "Because the exact same nonsense mutation of B3GALNT2 found in Friesian horses was also present in a MDDGA11 human patient with hydrocephalus, the same complex as in humans (including muscular dystrophy) might underlie the phenotype observed in Friesian horses." (PMID 26452345, 2015).
dystroglycanopathy (5 papers, 2013 to 2022). "Our group subsequently confirmed that variants in both B3GALNT2 and GMPPB can cause dystroglycanopathy." (PMID 23894383, 2013). "No clear genotype–phenotype correlations can be identified for B3GALNT2-related dystroglycanopathy." (PMID 35456500, 2022). "For example, when P18 and P19 with mutations in B3GALNT2 and P20 and P21 with mutations in GMPPB were first analysed by flow cytometry, variants in these genes had not yet been identified as the cause of a dystroglycanopathy." (PMID 23894383, 2013).
congenital muscular dystrophy (3 papers, 2014 to 2020). A muscular dystrophy that is characterized by diminished muscle tone (hypotonia), progressive muscle weakness and degeneration (atrophy), abnormally fixed joints, spinal rigidity, and delays in reaching motor milestones such as sitting or standing unassisted. "Individuals reported with B3GALNT2 mutations present with severe phenotypes, characterized by cobblestone lissencephaly, congenital muscular dystrophy, and other features indicative of WWS or slightly milder MEB/FCMD-like phenotypes." (PMID 29273094, 2017). "An additional candidate gene mapped in the linked region is GALNT2, a glycosylating enzyme similar to B3GALNT2 recently found mutated in another form of congenital muscular dystrophy, and also involved in the O-glycosylation of peptides in the Golgi apparatus." (PMID 25353622, 2014). "The list of candidate genes was further filtered based on expression data and association with other diseases, and the ensuing identification of mutations in high-ranked genes for congenital muscular dystrophies (B3GALNT2, GMPPB and B3GNT1) illustrated the validity of this approach." (PMID 25353622, 2014). "Recent discoveries of gene associations to diseases, like B3GALNT2, GMPPB and B3GNT1 to congenital muscular dystrophies, were prioritized in the ranked lists, suggesting a posteriori validation of our approach and predictions." (PMID 25353622, 2014).
Ataxia (2 papers, 2015 to 2022). Ataxia refers to impaired coordination of voluntary muscle movement. "Two variants (c.571C>T and c.1259delG) in the MSTO1 gene (NM_018116.3) and one variant (c.1068dupT) in the B3GALNT2 gene (NM_152490.2) detected in both of the affected siblings were related to cerebellar atrophy and ataxia." (PMID 36468072, 2022).
Hydrocephalus (2 papers, 2015 to 2016). Hydrocephalus is an active distension of the ventricular system of the brain resulting from inadequate passage of CSF from its point of production within the cerebral ventricles to its point of absorption into the systemic circulation. "Next generation DNA sequence analysis of 4 cases and 6 controls of gene exons within the region revealed a mutation in β-1,3-N-acetylgalactosaminyltransferase 2 (B3GALNT2) as the likely cause of hydrocephalus in Friesian horses." (PMID 26452345, 2015). "A nonsense mutation XM_001491545 c.1423C>T corresponding to XP_001491595 p.Gln475* in B3GALNT2 (1:75,859,296–75,909,376) is concordant with hydrocephalus in Friesian horses." (PMID 26452345, 2015). "The variant in the gene coding for β-1,3-N-acetylgalactosaminyltransferase 2 (B3GALNT2 [Ensembl:ENSECAG00000013338]) was a very likely candidate for the hydrocephalus phenotype." (PMID 26452345, 2015).
muscular dystrophy-dystroglycanopathies (2 papers, 2015 to 2017). "Searches of OMIM, OMIA, Ensembl and NCBI databases have not revealed associations between B3GALNT2 and a phenotype or disorder other than muscular dystrophy-dystroglycanopathy in humans." (PMID 26452345, 2015).
Blindness (1 paper, 2025). Blindness is the condition of lacking visual perception defined as a profound reduction in visual perception. "B3GALNT2-CMD is characterized by visual symptoms, including ocular involvement in ten cases, which features optic nerve hypoplasia, microphthalmia, and blindness." (PMID 40993721, 2025).
breast carcinoma (1 paper, 2022). "Furthermore, the B3GALNT2 mRNA has been found overexpressed (by 2.56-fold) in breast cancer samples, especially from patients with TNBC, although B3GALNT2 was detectably downregulated in rhabdomyosarcoma and kidney carcinoma (by ‒ 1.82-fold) biopsy samples." (PMID 36494657, 2022).
cervical carcinoma (1 paper, 2022). A carcinoma arising from either the exocervical squamous epithelium or the endocervical glandular epithelium. "Recently, WFA was shown to strongly interact with the LacdiNAc structure produced by human cervical carcinoma cells, and 1,3-N-acetylgalactosaminyltransferase 2 (B3GALNT2) is responsible for its biosynthesis." (PMID 36006984, 2022).
developmental delay (1 paper, 2022). "Here, we report a 7-year-old girl with a homozygous frameshift mutation in B3GALNT2, presenting with isolated global developmental delay and central nervous system abnormalities initially attributed to perinatal asphyxia." (PMID 35456500, 2022).
epilepsy (1 paper, 2017). A brain disorder characterized by episodes of abnormally increased neuronal discharge resulting in transient episodes of sensory or motor neurological dysfunction, or psychic dysfunction. "In this report, we describe two families affected with ID with and without epilepsy caused by mutations in B3GALNT2, a known gene associated with MDDG." (PMID 29273094, 2017).
mental disorder (1 paper, 2024). A disease that has its basis in the disruption of mental process. "The MIR9-3 Host Gene (MIR9-3HG), the lncRNA class-associated LOC341056 gene, and the Beta-1,3-N-Acetylgalactosaminyltransferase 2 (B3GALNT2) have not been reported to be related to a mental disorder phenotype before." (PMID 39367879, 2024).
tumor (2 papers, 2018 to 2022). "β-1,3-N-acetylgalactosaminyltransferase II (B3GALNT2) belongs to the β-1,3-glycosyltransferases (b3GT) family and has been reported to regulate development of both normal and tumor tissues." (PMID 29618368, 2018). "This study evaluated B3GALNT2 as a tumor marker in HCC and revealed functions of B3GALNT2 in metabolic transformation and microenvironmental remodeling in HCC." (PMID 29618368, 2018). "Intriguingly, in the subcutaneous tumor model, B3GALNT2 knockdown significantly suppressed tumor growth (p < 0.05) and B3GALNT2 overexpression promoted tumor growth (p < 0.05)." (PMID 29618368, 2018). "Similar results were observed in tumor tissues from HCC patients and revealed a significant positive correlation between tumor B3GALNT2 levels and the number of CD68-positive macrophages in the HCC microenvironment (R = 0.325, p < 0.001)." (PMID 29618368, 2018). "In summary, this study evaluated B3GALNT2 as a tumor marker in HCC and revealed the role of B3GALNT2 in metabolism which transformed the microenvironment of HCC." (PMID 29618368, 2018). "In this study, our data reveal that B3GALNT2 is upregulated in HCC, and this upregulation is associated with tumor growth and poor prognosis." (PMID 29618368, 2018). "The media functioned similarly to that of the secreting host, by proving that B3GALNT2 can promote macrophage infiltration via altering secretions from tumor cells." (PMID 29618368, 2018). "For expression analysis, higher levels of B3GALNT2 were observed in tumor tissues compared with adjacent normal tissues, and upregulation of B3GALNT2 correlated with increased tumor size and worse overall survival." (PMID 29618368, 2018). "Higher levels of B3GALNT2 in tumor tissues compared with adjacent normal tissues were observed in most samples (p < 0.001)." (PMID 29618368, 2018). "a–c Relative mRNA expression of B3GALNT2 in HCC tumor tissues and normal liver tissues obtained from GSE76427, GSE36376, and TCGA-LIHC datasets." (PMID 29618368, 2018). "Similar results were observed in liver orthotopic xenograft transplants (p < 0.05), and B3GALNT2 knockdown in orthotopic xenografts significantly improved survival of tumor-bearing mice (p = 0.0134)." (PMID 29618368, 2018). "Our study also determined how B3GALNT2 remodels the tumor microenvironments to promote tumor growth." (PMID 29618368, 2018). "In accordance with the mRNA levels, higher protein levels of B3GALNT2 in tumor tissues were also determined by Western blotting analysis." (PMID 29618368, 2018). "B3GALNT2 has been reported to regulate the development of both normal tissues and tumor tissues." (PMID 29618368, 2018). "The contradictory results of in vivo and in vitro tests also suggested that other than regulating tumor cells directly, B3GALNT2 might exert its function via modulating some other tumor-associated cells in vivo to promote tumor progression indirectly." (PMID 29618368, 2018). "Since tumor B3GALNT2 decreased acetoacetate levels we speculated that B3GALNT2-modulated effects on macrophage recruitment are associated with MIF activities." (PMID 29618368, 2018). "The functions of B3GALNT2 in tumor progression were evaluated in HCC cell lines and nude mice." (PMID 29618368, 2018). "Since HCC tumor cells and macrophages localized in different chambers in the transwell assays, we speculated that B3GALNT2 might modulate the secretion from tumor cells to promote macrophage infiltration." (PMID 29618368, 2018). "On the other hand, a series of other genes acting earlier in this pathway are overexpressed in tumor cells, namely DOLK, DPM1/2/3, POMGNT1, B3GALNT2, POMK and FKTN, hence exerting instead a pro-oncogenic role." (PMID 36494657, 2022). "To verify the expression pattern of B3GALNT2 in HCC, we examined mRNA levels of B3GALNT2 in 24 pairs of samples from HCC tumor tissues and matched adjacent normal tissues." (PMID 29618368, 2018).
tumor (continued). "Changing levels of B3GALNT2 did not influence cell viability in vitro but promoted tumor growth via enhancing macrophage recruitment in vivo." (PMID 29618368, 2018).
cancer (1 paper, 2018). A tumor composed of atypical neoplastic, often pleomorphic cells that invade other tissues. "Since knockdown of B3GALNT2 in zebrafish leads to degeneration of the extracellular matrix, B3GALNT2 might also exert functions in cancer progression via altering secretion or remodeling the extracellular environment." (PMID 29618368, 2018). "However, studies on the functions of B3GALNT2 in cancer are quite limited." (PMID 29618368, 2018).
neurodevelopmental disorder (1 paper, 2017). A behavioral and cognitive disorder with onset during the developmental period that involves impaired or aberrant development of intellectual, motor, or social functions. "Using linkage mapping and whole-exome sequencing in two families with an unexplained neurodevelopmental disorder, we have identified homozygous and compound heterozygous mutations in B3GALNT2." (PMID 29273094, 2017).
B3GALNT2 also shares sentences with these, for which no sentence is quoted: Walker-Warburg syndrome (3 papers); hepatocellular carcinoma (2); autism (1); autism spectrum disorder (1); Cerebellar atrophy (1); Cerebellar cyst (1); cobblestone lissencephaly (1); congenital hydrocephalus (1); kidney carcinoma (1); Mental Retardation (1); microphthalmia (1); optic nerve hypoplasia (1); recessive intellectual disability (1); rhabdomyosarcoma (1).